SYP (synaptophysin)
Diseases named in the same sentence as SYP in open-access papers (continued):
Sharing a sentence is not in itself a finding about the gene and the disease.
tumor (continued). "MiR-375 plays roles in neuroendocrine tissues and induces tumor cells to express SYP, NSE, and CHGA." (PMID 35938167, 2022). "Immunohistochemically, the tumor cells were positive for synaptophysin, chromogranin A, and calretinin and were focally positive for NeuN, TTF1, NF, CK8, vimentin, and S100 proteins." (PMID 35663322, 2022). "An endoscopic ultrasonographic fine needle aspiration (EUS-FNA) revealed a rosette-like aggregation of small round monotonous cells, and immunohistochemical staining showed that the tumor cells were positive for synaptophysin." (PMID 35754064, 2022). "The synaptophysin immunoreactivity was noted in >5% tumor area in 94 cores and was classified as NED (64.0%)." (PMID 35626098, 2022). "According to the model, five SCNEC cases were immunoreactive for synaptophysin in more than 20% of tumor cells and classified as NED." (PMID 35626098, 2022). "The sheet-like component consisted of homogenous tumor cells, with chromogranin A and synaptophysin diffusely positive, and a Ki-67 index of 72.8%." (PMID 35596001, 2022). "Diffuse and intense cytoplasmic expression of synaptophysin and chromogranin A and nuclear staining for insulinoma-associated 1 (INSM1) reveals the tumor’s neuroendocrine differentiation, the common denominator of NENs." (PMID 34647171, 2022). "The tumor cells typically show a loss of GFAP expression, but express neuronal markers such as synaptophysin or NSE." (PMID 36414742, 2022). "Pathologic evaluation of the 3.1 × 1.9 cm tumor revealed an LCNEC with immunohistochemical positivity at Synaptophysin, EMA, CD56, and cytokeratin CK8/18." (PMID 35892508, 2022). "Depending on their degree of differentiation, tumour cells express positive to neuron-specific enolase, synaptophysin, and S-100 protein." (PMID 35633271, 2022). "Although the expression of CHGA, NCAM1, and SYP varied among these three individuals, all of them showed a co-expression of AR and NE markers in the same areas of tumor sites." (PMID 36033483, 2022). "Growth characteristics and survival of synaptophysin-positive cells in PPGL tumour cultures showed wide variation, some of which appeared attributable to the culture medium." (PMID 36178902, 2022). "The markers that distinguished G3 tumours from the lower grades were higher levels of synaptophysin, CD56, Ki-67, CD24, CD44, β-catenin and E-cadherin." (PMID 36362433, 2022). "The same tumor cells were also positive for the neuroendocrine markers Synaptophysin (SYP) and Chromogranin (CHGA)." (PMID 35789568, 2022). "In immunohistochemistry, the most useful markers are neural cell adhesion molecules (CD56), chromogranin and synaptophysin.CD56 will stain the tumour in approximately 90–100% of cases." (PMID 36035652, 2022). "Positive expression of H-caldesmon and synaptophysin were detected in 13 cases (87%), of which synaptophysin positivity varied from 10% of tumor cells to global immunoreactivity (median of positive tumor cells 70%)." (PMID 36699621, 2022). "By immunohistochemistry, 71% (9/13) of NEC were extensively (≥90% tumor cells) positive for synaptophysin (8/13, 62%) and/or chromogranin (4/13, 31%), with two others (SCNEC5 and ANEC1) showing patchy staining for both neuroendocrine markers." (PMID 35590107, 2022). "Immunohistochemistry of the tumor reveals positive synaptophysin and chromogranin staining in chief cells, and positive S-100 and negative cytokeratin staining in sustentacular cells." (PMID 35804996, 2022). "A study from Wiedenmann and co-authors concluded that synaptophysin was expressed independently of other neuronal differentiation markers and proposed that it be used as a differentiation marker in tumor diagnosis." (PMID 35631574, 2022). "Using multiplex immunofluorescence staining, we detected AR and SYP simultaneously in tumor samples consisting of both premalignant prostate lesions and malignant tumor tissues." (PMID 36033483, 2022).
tumor (continued). "Given the loss of GFAP and the expression of synaptophysin and CD56 in the new clival biopsy, the tumor did certainly show the immunohistochemical features of a glioblastoma with a neuronal component." (PMID 36414742, 2022). "A small subset of iGRP LGGs contained glial/embryonal tumor areas that were moderately immunopositive for synaptophysin." (PMID 35986378, 2022). "Synaptophysin-positive PPGL tumour cells persist in culture for long periods but show little evidence of proliferation." (PMID 36178902, 2022). "Those tumor cells were positive for synaptophysin and focally positive for chromogranin A, indicating neuroendocrine differentiation." (PMID 36434637, 2022). "PDX tumors and spheroids both expressed CD56 and synaptophysin in concordance with the primary tumor." (PMID 35565191, 2022). "Immunohistochemical staining of the tumors showed that the positive rates of chromogranin A (CgA) and synaptophysin (Syn) were 21/23 and 13/13, respectively, which showed varying numbers of brown granules in the cytoplasm of tumor cells." (PMID 35558392, 2022). "The pleomorphic component was diverse and prominent atypical tumor cells proliferated, focally positive for chromogranin A, diffusely positive for synaptophysin, and the Ki-67 index was 67.1%." (PMID 35596001, 2022). "Of note, the implementation of synaptophysin as a dynamic liquid biomarker, via its expression on circulating tumor cells (CTCs) for example, remains challenging." (PMID 34064565, 2021). "The tumor consists of amyloid-deposited fibrous stroma and polygonal tumor cells with strong immunoreactivity for thyroid transcription factor-1 and synaptophysin." (PMID 34803914, 2021). "The expression of synaptophysin ranged from single scattered synaptophysin-positive tumor cells to a strong and diffuse expression in almost all tumor cells." (PMID 34680258, 2021). "The third group encompassed 15 carcinomas with synaptophysin-positive cells ranging from 10–29% (15/239; 6%) and the fourth group had 14 carcinomas with a diffuse synaptophysin staining of 30–99% of all tumor cells (14/239; 6%)." (PMID 34680258, 2021). "Immunohistochemically, the tumor was positive for chromogranin A, synaptophysin, and CD 56, and the Ki-67 index was 40%." (PMID 34727269, 2021). "While all but one tumor expressed synaptophysin, mostly patchy, only 10/29 (34%) co-expressed chromograninA." (PMID 34350470, 2021). "A biopsy of the retroperitoneal mass was performed and was suggestive of a paraganglioma (tumour cells reactive with chromogranin and synaptophysin); for this reason, Endocrinology observation was required." (PMID 33815275, 2021). "The most common tumour studies for diagnosis were chromogranin A and synaptophysin; serum chromogranin A and urinary 5-HIAA were also used frequently." (PMID 34109562, 2021). "Immunohistochemically, the tumor cells were positive for synaptophysin, chromogranin A, and CD56, indicating neuroendocrine differentiation." (PMID 33388069, 2021). "In contrast to the other MN-NEs with their patchy staining, synaptophysin (as well as chromograninA) labeled the FUS-CREM neoplasm diffusely." (PMID 34350470, 2021). "Immunohistochemical analysis showed that the tumor cells are strongly positive for cytokeratin (AE1/AE3) and insulinoma-associated protein 1 (INSM-1), and scatteredly positive for chromogranin A, synaptophysin, and CD56, supporting the diagnosis." (PMID 34477164, 2021). "Immunohistochemically, the tumor exhibited diffuse positivity for the expression of chromogranin A and synaptophysin and negativity for the expression of CD56." (PMID 34727269, 2021). "The second largest group contained adenocarcinomas with a range from >1–9% of scattered synaptophysin-positive tumor cells (72/239; 30%)." (PMID 34680258, 2021). "The extra-adrenal tumour was suggestive of well differentiated neuroblastoma (tumour cells reactive with neurofilaments, chromogranin, synaptophysin, NSE and S100) with a Ki-67 index of 10%." (PMID 33815275, 2021).
tumor (continued). "Platelet-expressed synaptophysin (pSyn) was found to be significantly upregulated during tumor progression." (PMID 34064565, 2021). "Immunohistostaining studies revealed that the tumor cells were positive for vimentin, synaptophysin, cluster of differentiation (CD) 56, β-catenin, CD10, and progesterone receptor." (PMID 33650037, 2021). "In this case, for example, glial and neural markers (glial fibrillary acidic protein, S100, or synaptophysin) were positively expressed by the donor tumor cells but were undetected in the recipient lesions." (PMID 34301805, 2021). "Both components invaded through the adventitia with the deeper infiltrating tumor exhibiting strong expression of the neuroendocrine markers chromogranin and synaptophysin." (PMID 34122537, 2021). "These GEP-NET PDCOs maintained proliferation rates similar to the original tumor along with synaptophysin and chromogranin A expression that is characteristic of neuroendocrine cells." (PMID 33919802, 2021). "Immunohistochemical studies revealed that the tumor cells were positive for vimentin, synaptophysin, CD56, β-catenin, CD10, and progesterone receptor." (PMID 33650037, 2021). "Remarkably, compared to patients displaying a weak to moderate staining intensity in the tumor, patients showing a strong or very strong synaptophysin staining displayed higher pSyn level." (PMID 34064565, 2021). "Organoids largely resembled the original tumor in expression of synaptophysin, chromogranin and Ki-67." (PMID 33776923, 2021). "Accordingly, we analyzed platelet-expressed synaptophysin (pSyn) level in the subgroup of patients displaying an active tumor disease and compared them with patients receiving follow-up care." (PMID 34064565, 2021). "In a consultation series of 4498 cases collected between 2009 and 2021, 2099 neoplasms expressing synaptophysin and/or chromograninA were reviewed and analyzed." (PMID 34350470, 2021). "In these neoplasms, synaptophysin was recorded in approximately half to two-thirds of the cases, making synaptophysin an important “pitfall marker” in these neoplasms." (PMID 34350470, 2021). "Immunohistochemically, the tumor exhibited diffuse positivity for the expression of chromogranin A and synaptophysin and focal positivity for the expression of CD56." (PMID 34727269, 2021). "Platelet-expressed synaptophysin was significantly correlated with tumor proliferation and metastasis, demonstrating the involvement of platelets in tumor biology." (PMID 34064565, 2021). "The tumor cells arranged in lobules and papillae were immunopositive for chromogranin and synaptophysin, while the spindle-shaped cells were immunopositive for S-100." (PMID 34307231, 2021). "Immunohistochemically, the tumor cells were positive for cytokeratin, chromogranin, synaptophysin, and CD56." (PMID 32245475, 2020). "By immunohistochemistry, the tumor cells were strongly positive for synaptophysin, and the Ki67 proliferation index was high (>50%)." (PMID 33344249, 2020). "Synaptophysin, with its small clear vesicles in tumor cells, and chromogranin, with its large neurosecretory granules, are usually stained diffusely in NEN." (PMID 32632765, 2020). "An immunohistochemical analysis of the tumor showed positive staining for synaptophysin and chromogranin antibodies." (PMID 32156307, 2020). "Immunohistochemistry (IHC) staining for chromogranin A and synaptophysin, both of which are neuroendocrine markers, was diffusely and strongly positive in the tumor cells." (PMID 33031286, 2020). "Diffuse CD99, ERG, CD56, focal PanCK, Cam5.2 and Synaptophysin immune positivity are characteristic for Ewing sarcoma family of tumours." (PMID 32450834, 2020). "Histopathological analysis of Synaptophysin as a neuroendocrine marker within the tumor tissue revealed expression only within NEC." (PMID 32927768, 2020).
tumor (continued). "Theanatomopathological study of the specimens included evaluation of themargins and immunohistochemistry (chromogranin, synaptophysin and Ki 67) tocharacterize the tumor." (PMID 32844878, 2020). "In the immunohistochemical analysis, tumor cells were positive for NSE, chromogranin, and synaptophysin, which suggested that the tumor had a neuroendocrine feature." (PMID 32562013, 2020). "At the same time, this stain allows SKIE to quantify the Ki-67-positive tumor nuclei, which are presumed to be Ki-67 positive cells within the synaptophysin-positive tumor regions." (PMID 32632119, 2020). "All 163 tumours were immunoreactive for synaptophysin, 107 (66%) for chromogranin A and the median Ki67-index was 90% (range: 21–100%)." (PMID 31924180, 2020). "Tumor cells exhibit variable immunopositivity for neuroendocrine markers like synaptophysin, chromogranin, and CD56." (PMID 32335641, 2020). "The expression of SSTR-2a, CgA and synaptophysin was analysed in tumour specimens by immunohistochemistry, and semi-quantitatively scored as negative (< 5%), heterogeneously positive (5–30%) or strongly positive (> 30%)." (PMID 31924180, 2020). "At immunohistochemical analysis, tumor cells stained positive with synaptophysin, chromogranin, cytokeratin, and neuron-specific enolase (NSE)." (PMID 32156307, 2020). "The immunohistochemistry (IHC) analyses showed that tumor cells were positive for thyroid transcription factor-1 (TTF-1) and neuroendocrine markers, including chromogranin A, synaptophysin, INSM1 (insulinoma-associated protein 1), and CD56." (PMID 33352665, 2020). "One limitation of SKIE is that this method cannot differentiate cell types within synaptophysin-positive tumor regions." (PMID 32632119, 2020). "By immunohistochemistry, the tumor cells were seen positive for Chromogranin A, Synaptophysin, CD56, INSM1, OSCAR, somatostatin receptor type 2 (SSR2), P16 and focally for ISLET1." (PMID 32854635, 2020). "The tumor cells composed of perivascular pseudorosettes showed positivity for both synaptophysin and glial markers such as GFAP and Olig2." (PMID 31804365, 2019). "Both small and large patient-derived tumorspheres, as well as Y79 cells, were positive stained for arrestin 3 and synaptophysin, confirming the retinal and neuroectodermic tumor cell origin." (PMID 30832308, 2019). "Immunohistochemically, the tumor cells were positive for neuroendocrine markers (chromogranin A, synaptophysin, CD56) and thyroid transcription factor-1 (TTF-1)." (PMID 31511024, 2019). "Young adult age, synaptophysin positive tumor, lymphocytic cuffs, and a high Ki67 level (mean 2.5%) have been shown to be associated with the BRAF V600E mutated status." (PMID 30984614, 2019). "The TMP panel included 7 proteins routinely used in diagnostic IHC including cytokeratins (KRT5 and KRT7), markers of stratified epithelia (P63), mesenchymal (Vimentin) and neuroendocrine (CHGA, SYP) differentiation, and primary tumour origin (TTF1)." (PMID 31537838, 2019). "Typical histopathologic findings include small island forming Zellballen nests and chromogranin and synaptophysin immunohistochemical staining for tumour cells." (PMID 31731083, 2019). "Immunohistochemically, the tumor cells were positive for chromogranin A, synaptophysin, CD56, and TTF-1 and the Ki-67 index was 27%." (PMID 31511024, 2019). "Morphological analysis of tumour xenografts showed neuroendocrine differentiation with strong immunohistochemical staining for synaptophysin, chromogranin A, serotonin and pan-cytokeratin." (PMID 30730850, 2019). "Results from IHC staining of the NE markers (SYP and ChgA) in tumor tissues of Enz-treated mice also indicated that Enz significantly increased the NED." (PMID 31189930, 2019). "Pathological analysis revealed tumor cells positive for chromogranin A, synaptophysin and for S-100." (PMID 31689630, 2019).
tumor (continued). "The tumours were also stained positively with other neuroendocrine markers, e.g., chromogranin A (39 positive/42 tested) and synaptophysin (32/35)." (PMID 30425741, 2018). "Immunohistochemically, tumor cells showed positivity for chromogranin A and synaptophysin; Ki-67 index was < 1.0%." (PMID 30037336, 2018). "Chen and coworkers were able to show similar results through isolation of CD133 and NESTIN-expressing cells from PA, which were able to initiate synaptophysin-positive tumours when xenotransplanted subcutaneously." (PMID 28855316, 2018). "Both xenograft tumours showed substantial positivity for human synaptophysin mainly in the invasion zone and in the boundaries of the tumours." (PMID 30297697, 2018). "To exclude that the synapse-like structures correspond to a cell culture artefact, we further analyzed tumour material from xenograft tumours from the GSC lines R8 (slightly synaptophysin positive) and the GSC line R28 (strongly synaptophysin positive)." (PMID 30297697, 2018). "The tumor architecture is the most important diagnostic feature for MANEC, which is then confirmed by immunohistochemical findings such as chromogranin A, synaptophysin, CD56, and neuron-specific enolase expression." (PMID 29740725, 2018). "In vivo, vGlut1 mRNA expression correlated very strongly with synaptophysin expression in microarrays available to the RemBraNDT (REpository for Molecular BRAin Neoplasia DaTa) database (Pearson r = 0.92, p < 0.001)." (PMID 30297697, 2018). "All tumours ought to be examined for endocrine differentiation by immunohistochemistry with antibodies towards general NE markers like chromogranin A and synaptophysin." (PMID 30567376, 2018). "Tumors deriving from A99 and TCC-NECT-2 were diffusely positive for chromogranin A and synaptophysin, and tumor deriving from TYUC-1 was focally positive for both of them." (PMID 29765522, 2018). "We therefore compared these areas directly to human PNET sections, and found that they shared several histological features, including a less pronounced desmoplastic tumor stroma and stained positive for the neuroendocrine marker Synaptophysin." (PMID 30135483, 2018). "Immunohistochemically, tumor cells showed the expression of chromogranin A and synaptophysin, and a Ki-67 index < 1.0%." (PMID 30037336, 2018). "A detailed immunohistochemical analysis showed that the tumor was strongly positive for synaptophysin, CD56 and chromogranin A, with a Ki-67 labeling index greater than 80%." (PMID 30024526, 2018). "Immunostaining revealed that the tumor cells were positive for chromogranin A, synaptophysin, and CD56." (PMID 29218566, 2018). "Higher percentages of Cytokeratin-Synaptophysin dual positive tumor cells correlate with shortened disease-free survival." (PMID 29170413, 2017). "We followed up on this observation, assessing the extent of neuroendocrine differentiation in the patient's tumor by assessing the expression of synaptophysin and chromogranin A using IHC assays commonly implemented in the anatomic pathology laboratory." (PMID 28835367, 2017). "Immunohistochemical staining for the NE markers chromogranin A and synaptophysin showed strong staining of the tumor cells." (PMID 28097640, 2017). "All tumor tissues were immunoreactive for either one or both neuroendocrine biomarkers (chromogranin A and synaptophysin) and Ki67 index was >20% in all cases." (PMID 29112960, 2017). "The immunohistochemical staining in this study showed that the tumor cells experssed synaptophysin, NSE, MAP-2 and S-100 in two cases." (PMID 28977976, 2017). "The tumor stained positively with several neuroendocrine markers including chromogranin A, synaptophysin and somatostatin receptor-2." (PMID 28378747, 2017). "It is also worth noting that in these studies we observed single YFP + SYP + cells within the tumor stroma." (PMID 29170413, 2017).